CRP (C-reactive protein)
Diseases named in the same sentence as CRP in open-access papers (continued):
Sharing a sentence is not in itself a finding about the gene and the disease.
prostate carcinoma (92 papers, 2004 to 2025). A carcinoma that arises from epithelial cells of the prostate gland. "Meta-analytic evidence demonstrates that elevated circulating CRP levels are associated with increased overall mortality in prostate cancer patients, particularly those with metastatic or castration-resistant disease." (PMID 41555998, 2025). "Their study revealed that elevated plasma CRP levels (≥ 8.6 mg/L) were associated with poorer cancer-specific survival, overall survival, and disease-free survival in prostate cancer patients." (PMID 40178629, 2025). "Biomarkers such as C-reactive protein (CRP) have been linked to cardiovascular risk, while saliva has been explored for cancer detection, including pancreatic and prostate cancers." (PMID 39958008, 2025). "Patients with solid tumors (breast, lung, or prostate cancer) and elevated CRP levels at the time of diagnosis were associated with poor prognosis." (PMID 39001318, 2024). "Several inflammatory indices (IL-6, TNFR2, and CRP) are positively associated with prostate cancer progression." (PMID 39519548, 2024). "This aspect was noted in another comparative study from the literature for CRP, which is considered an independent predicting factor of cancer-specific survival in prostate cancer patients near AGP-1 and is also associated with cancer progression." (PMID 39452544, 2024). "In this study we studied factors associated with the development of CRP in prostate cancer patients." (PMID 39132647, 2023). "Given the intimate proximity of prostate cancer to the anterior rectal wall, we postulate that prostate cancer effects matrix vascular mimicry, predisposes the rectum to CRP, and this effect is preventable by amifostine, statins, and NSAIDs." (PMID 39132647, 2023). "We identified an inverse potential causal association between genetically elevated CRP levels and risk of prostate cancer." (PMID 35459240, 2022). "In line with this, high levels of acute phase proteins in plasma, like C-reactive protein, are associated with disease aggressiveness in prostate cancer patients." (PMID 35551231, 2022). "Subgroup analysis showed that there was an interaction between CRP and smoking status on risk for overall cancer, lung, uterus, and prostate cancer." (PMID 36117174, 2022). "C-reactive protein (CRP) is a commonly measured pro-inflammatory marker in the bodyand has been reported to be associated with worse prostate cancer prognosis." (PMID 35365620, 2022). "In a similar retrospective, institutional study of 700 patients undergoing radiation for prostate cancer, a pre-treatment CRP ≥8.6 mg/L was associated with worse cancer-specific survival, overall survival, and clinical disease-free survival." (PMID 34512646, 2021). "There is some evidence that elevated levels of CRP are associated with increased risk of prostate cancer development, PSA, Gleason score, and decreased response to chemotherapy and radiotherapy (RT)." (PMID 34926085, 2021). "The association of elevated CRP levels with clinical response for kidney, bladder, and prostate cancer." (PMID 34512646, 2021). "For instance, a cohort study including 8,471 Swedish participants found that men with high CRP levels (≥10 mg/L) had 29% (95% CI 7 to 56%) increased the odds of prostate cancer risk compared with those with low CRP level (<10 mg/L)." (PMID 33178578, 2020). "In this study, we applied a two-sample Mendelian randomization (MR) approach to evaluate the potential causal association of circulating CRP levels with prostate cancer risk." (PMID 33178578, 2020). "Because circulating C-reactive protein (CRP) is an important biomarker for low-grade chronic inflammation, the association of this biomarker with the incidence of prostate cancer has been investigated in several observational epidemiological studies." (PMID 33178578, 2020). "Previous studies have shown that inflammatory cytokines, including CRP, IL-6, and IL-17, are positively associated with the risk of prostate cancer." (PMID 31088536, 2019).
prostate carcinoma (continued). "A recent study showed that elevated CRP level was associated with poor prognosis in prostate cancer patients treated with radiotherapy." (PMID 28423553, 2017). "In this study, we explored which among the fractions of white blood cell (WBC) and C-reactive protein (CRP) level were associated with high Gleason score prostate cancer." (PMID 27823973, 2017). "It has been well documented that both CRP and Hcy have been reported to be associated with a high risk of prostate cancer, which usually occurs in elderly male persons." (PMID 26217177, 2015). "For CRP, men with a low risk of cancer by CRP measure had slightly higher odds of having prostate cancer." (PMID 26380255, 2015). "Several lines of evidence also indicated that the elevated serum CRP levels were correlated to the high risk of prostate cancer and its assessment." (PMID 26217177, 2015). "Of the proteins previously associated with prostate cancer; CRP is an acute phase reactant (APR) protein produced by the liver in response to inflammation." (PMID 22355332, 2012). "In prostate cancer patients, a strong association between the levels of serum C-reactive protein (CRP) and serum PSA has been reported." (PMID 22110995, 2011). "Since tumoural CRP is likely to have a role in progression of prostate cancer, it was suggested by authors that CRP is associated with increased presence of metastases at the time of diagnosis and time of relapse." (PMID 22110984, 2011). "From the Apolipoprotein MOrtality RISk (AMORIS) study with repeated measurements of CRP in a prospective cohort study noted a positive trend between CRP and risk of developing prostate cancer and concluded a link between inflammatory markers and cancer risk." (PMID 22110984, 2011). "Notably, while observational studies have suggested associations between pre-diagnostic CRP levels and prostate cancer incidence, recent Mendelian randomization analyses have questioned the causal nature of these associations." (PMID 41555998, 2025). "As cancer itself is known to be a driver of inflammation and activation of hemostasis, we evaluated the difference in CRP levels and hemostatic biomarkers in the subgroup of patients with tumor types considered to have a low thrombotic risk (breast and prostate cancer)." (PMID 40524734, 2025). "We seek to establish whether CRP levels reflect inflammation caused by prostate cancer by comparing levels at various points of time before, during, and after therapy." (PMID 34926085, 2021). "Findings regarding an association between CRP levels and prostate cancer risk have been mixed." (PMID 34926085, 2021). "Findings regarding the correlation between prostate cancer risk and CRP have also been mixed." (PMID 34926085, 2021). "CRP levels have been shown to be associated with the probability of a prostate cancer diagnosis in patients with elevated PSA, the probability of biochemical recurrence following definitive treatment for localized prostate cancer, and decreased overall survival for patients with advanced disease." (PMID 34512646, 2021). "Therefore, in this study, we aimed to evaluate potential causal association of circulating CRP levels with risk of prostate cancer, using the two-sample MR study design." (PMID 33178578, 2020). "To assess the influence of potential pleiotropy on the causal effect estimate of the relationship between circulating CRP levels and risk of prostate cancer, we performed a series of sensitivity analyses, including the weighted-median method, MR-Egger regression, and MR-PRESSO test." (PMID 33178578, 2020). "Because conventional observational studies are susceptible to confounding and reverse causality, it remains unclear whether there is a causal relationship of CRP with risk of prostate cancer." (PMID 33178578, 2020). "However, observational findings regarding the association of CRP with risk of prostate cancer were inconsistent." (PMID 33178578, 2020).
prostate carcinoma (continued). "We examined CRP as an inflammatory indicator of the risk of prostate cancer." (PMID 26380255, 2015). "Using the 2009–2010 National Health and Nutrition Examination Survey, we examined the relationships between demographic variables, inflammation, infection, circulating plasma C-reactive protein (CRP), and the risk of occurrence of prostate cancer in US men over 18 years of age." (PMID 26380255, 2015). "In a prospective study, CRP appeared unrelated to prostate cancer risk." (PMID 22110984, 2011). "Third, CRP is only one of the inflammatory markers, and a recent study has reported that genetically predicted circulating concentrations of several inflammatory-related cytokines were associated with the risk of breast, endometrial, lung, ovarian, and prostate cancer." (PMID 36117174, 2022). "Raised acute phase reactants (C reactive protein (CRP) (adjusted HR per SD 1.35 95% CI 1.02 to 1.77)), ferritin (adjusted HR per SD 2.03; 95% CI 1.21 to 3.39) and random glucose (adjusted HR per SD 1.27; 95% CI 1.06 to 1.54) were associated with prostate cancer mortality." (PMID 33579772, 2021). "C-reactive protein (CRP), an acute-phase reactant produced by hepatocytes in response to IL-6 signaling, has been extensively studied as an inflammatory biomarker in prostate cancer." (PMID 41555998, 2025). "C-reactive protein (CRP), a hallmark of inflammation, has been investigated as a prognostic marker in prostate cancer." (PMID 40178629, 2025). "Given the relationship between obesity, proinflammatory factors (e.g., IL-6, TNFR2, and CRP), and prostate cancer progression, we also examined the effect of a KD on markers of inflammation." (PMID 39519548, 2024). "From 1987–2002 there were 1177 prostate cancer patients diagnosed at our center and 63 patients were found to have endoscopy-proven CRP." (PMID 39132647, 2023). "This profile summarizes an analysis of the effect of pre-treatment C-reactive protein on three clinical outcomes (cancer-specific survival, overall survival, and disease-free survival) in prostate cancer patients." (PMID 35546237, 2022). "The analyses using cis-acting CRP IVs which survived the Bonferroni threshold was prostate cancer (β = −0.104, p = 0.002)." (PMID 35459240, 2022). "In more advanced type of prostate cancer (MCRPC), splice-disrupt variants, located on CDs of NCOR2, PTPRC, and CRP, are the high-risk variants." (PMID 35286517, 2022). "We have opted to use luminescence modulating phages for the analysis of known acute inflammatory response biomarker CRP (C-reactive protein) and biomarkers of prostate cancer in urine samples." (PMID 35165329, 2022). "Several studies have looked at the CRP levels of patients with metastatic castration-resistant prostate cancer." (PMID 34926085, 2021). "For prostate cancer, the role of CRP is fairly limited with prognostic utility observed in some, but not all settings." (PMID 34512646, 2021). "In a population-based, prospective study of 7,270 men followed for a mean of 11.8 years with serial inflammatory marker measurements, a CRP rise ≥ 1.0 mg/l between two measurements purported a 36% increase in subsequent prostate cancer diagnosis." (PMID 34512646, 2021). "Factors associated with an increased risk of prostate cancer mortality included age; high PSA; current or ex-smoker; ischaemic heart disease; high C reactive protein; high ferritin; low haemoglobin; high blood glucose and low albumin." (PMID 33579772, 2021). "We used this marker along with WBCs and lymphocytes to investigate the role of CRP in prostate cancer-based inflammation and the body’s inflammatory response." (PMID 34926085, 2021). "Based on the evidence that potential inflammatory processes can affect the pathogenesis and the progression of cancer, CRP has been suggested to be an important biomarker for urological cancers including prostate cancer." (PMID 33178578, 2020).
prostate carcinoma (continued). "According to an early report, CRP is an independent prognostic factor for overall survival of patients with castration-resistant prostate cancer treated with docetaxel." (PMID 28423553, 2017). "By contrast, serum C-reactive protein (CRP) and interleukin (IL)-8, two inflammatory molecules, were elevated in patients with prostate cancer." (PMID 28423553, 2017). "The aim of this study was therefore to explore which parameters among serum WBC count and the fractions of WBCs and CRP and NLR and MLR are associated with high Gleason score prostate cancer." (PMID 27823973, 2017). "By contrast, serum CRP and IL-8 levels were higher in patients with Grade 3 prostate cancer than in patients with Grade 1-2 prostate cancer." (PMID 28423553, 2017). "By contrast, serum CRP, a marker of systemic inflammation, was elevated in patients with prostate cancer." (PMID 28423553, 2017). "In previous studies, blood data, such as serum hemoglobin, alkaline phosphatase, lactate dehydrogenase, and C-reactive protein were reported as survival predictive factors for patients with prostate cancer." (PMID 26896160, 2016). "MetS features are known to accompany a pro-inflammatory state (elevated levels of C-reactive protein, TNF-α, interleukin 8, 6, 1β), which in turn has been related to prostate cancer risk." (PMID 27386844, 2016). "In previous studies, patient age and blood data such as serum Hb, alkaline phosphatase, LDH and CRP levels have been reported as predictive factors for patients with prostate cancer." (PMID 26883015, 2016). "During the last decade, numerous studies explored the prognostic impact of CRP in urological cancers, including renal cell cancer, prostate cancer, bladder cancer and upper urinary urothelial carcinoma." (PMID 26235332, 2015). "High CRP yielded a worse survival in renal cell carcinoma, prostate cancer, bladder cancer, and upper urinary tract urothelial carcinoma." (PMID 26235332, 2015). "Our pilot study demonstrated that NHANES can be used to examine relationships between CRP, demographic variables, inflammation, and prostate cancer." (PMID 26380255, 2015). "In contrast, recent studies have shown that CRP participates in tumor proliferation and high serum concentrations of CRP were correlated with shorter overall survival in patients with castration-refractory prostate cancers." (PMID 26380255, 2015). "CRP levels have been shown to predict survival in patients with renal cell carcinoma, bladder cancers, and prostate cancer, and the incorporation of CRP into prognostic models for those cancers improves the models' predictive accuracy." (PMID 26222696, 2015). "Using IBM SPSS, we performed bivariate and logistic regression analyses using high CRP values as the dependent variable and five study covariates including prostate cancer status." (PMID 26380255, 2015). "For example, in a retrospective study of 160 patients from the ASCENT (Androgen- Independent Prostate Cancer Study of Calcitriol Enhancing Taxotere) trial, CRP levels appeared to be a predictor of poorer survival." (PMID 23768149, 2013). "For patients with prostate cancer, the percentage decrease in CRP concentration after treatment was higher when the patient had more frequent treatments." (PMID 22963460, 2012). "This is consistent with other work demonstrating that plasma CRP levels are well-correlated with serum PSA levels in prostate cancer patients." (PMID 22963460, 2012). "Although elevated CRP concentrations have demonstrated prognostic relevance in prostate cancer, serving as an indicator of cancer-specific survival, its limited sensitivity for detecting chronic, localized inflammation in BPH reduces its diagnostic utility in this context." (PMID 40689176, 2025). "CRP has prognostic potential for patients with prostate cancer treated with radiation." (PMID 34512646, 2021). "Relationships between baseline CRP, high-risk prostate cancer, and elevated PSA have been reported but not consistently replicated." (PMID 34926085, 2021).
prostate carcinoma (continued). "Some prospective studies found a positive association of CRP with risk of prostate cancer, but others did not provide evidence to support this relationship." (PMID 33178578, 2020). "After exclusion of these SNPs, the MR effect estimate of circulating CRP levels on prostate cancer risk did not change essentially (OR 1.04, 95% CI 0.91 to 1.19, and P = 0.54 using the IVW method)." (PMID 33178578, 2020). "Hence, further longitudinal studies and MR analysis based on individual-level data as well as in vivo and in vitro functional studies are warranted to clarify the exact role of CRP in the development of prostate cancer." (PMID 33178578, 2020). "Collectively, these findings did not provide evidence for the causal effect of CRP on prostate cancer risk." (PMID 33178578, 2020). "The Prostate Cancer Study throughout Life (PROCA-life) investigating potential relationship between high sensitive CRP (hs-CRP) levels and white blood cell count (WBC) demonstrated that a significant increase in hs-CPR levels was associated with high PCa risks." (PMID 32843909, 2020). "The association between genetically predicted circulating CRP levels and prostate cancer risk did not change markedly after excluding these outlier SNPs (OR 1.02, 95% CI 0.95 to 1.08, and P = 0.64)." (PMID 33178578, 2020). "Interestingly, serum CRP and IL-8 levels were significantly higher in patients with prostate cancer than in controls." (PMID 28423553, 2017). "By contrast, serum CRP and IL-8 were increased in patients with prostate cancer." (PMID 28423553, 2017). "Interestingly, serum CRP level was significantly increased in patients with Grade 3 prostate cancer than in patients with Grade 1-2 prostate cancer." (PMID 28423553, 2017). "Serum TNF-α, CRP and IL-8 levelswere analyzed in patients with prostate cancer and controls." (PMID 28423553, 2017). "Interestingly, serum 25-(OH)D was negatively correlated with serum CRP level in patients with prostate cancer (r=-0.286, P<0.05)." (PMID 28423553, 2017). "Serum 25-(OH)D was negatively correlated with serum CRP and IL-8 in patients with prostate cancer." (PMID 28423553, 2017). "CRP could predict tumor aggressiveness and potential treatment efficacy in patients with prostate cancer." (PMID 28423553, 2017). "Other variables in the logistic regression model (race/ethnicity, annual household income, education, and age) were used to control for confounding effects between the variables of high CRP values (the dependent variable) and prostate cancer (the independent variable)." (PMID 26380255, 2015). "It is therefore important to further investigate the relationship between CRP and prostate cancer." (PMID 26380255, 2015). "These men with high CRP values had lower odds of having received higher education, being aged 40 years or older, being of a race or ethnicity different from other, and of having prostate cancer." (PMID 26380255, 2015). "More recently, systemic inflammation based prognostic scores such as the modified Glasgow Prognostic Score (mGPS, a combination of C-reactive protein and albumin), have been developed and found to have significant prognostic value in one-year and five-year survival from prostate cancer." (PMID 23768149, 2013). "Interleukin-6 (IL-6) and CRP were reported to be elevated in prostate cancer patients and IL-6 may potentially be involved in the development or progression of prostate cancer." (PMID 22110984, 2011). "Moreover, preoperative CRP values and comparison to the postoperative values could have been useful in investigating changes in intrinsically high CRP values in prostate cancer patients." (PMID 38592056, 2024). "Consequently, targeting prostate cancers characterized by elevated CRP levels or increased PGE-2 production mediated by COX-1/2 with anti-inflammatory or immunomodulatory strategies could serve as a beneficial adjunct." (PMID 39267848, 2024).